EGFR (epidermal growth factor receptor)
Diseases named in the same sentence as EGFR in open-access papers (continued):
Sharing a sentence is not in itself a finding about the gene and the disease.
tumor (continued). "This construct combines the block of HER2/HER3 pathway and silencing of EGFR by the selective delivery of EGFR siRNA, resulting in an effective tumor inhibition in vivo." (PMID 30384431, 2018). "ADORA2B-expression was significantly correlated with ER (P < 0.01), PgR (P = 0.027), EGFR (P < 0.01), and tumor size (P = 0.037), and was an independent prognostic factor for outcome (P = 0.036)." (PMID 30349649, 2018). "We evaluated the in vitro and in vivo feasibility of 64Cu-PCTA-cetuximab, an immuno-PET imaging biomarker, in EGFR-expressing ESCC tumor models." (PMID 30373221, 2018). "It has been reported that integrins mediate the adhesion and migration properties of tumour cells by cooperating with specific growth factor receptors, such as EGFR." (PMID 30559931, 2018). "Subsequent NIR-PIT using can225-IR700 induced remarkable therapeutic responses after only a single injection of the conjugate and two NIR light exposures in an EGFR-expressing canine xenograft tumor model." (PMID 29721181, 2018). "The phosphorylation of GPRC5A in two conserved double-tyrosine (TYR) motifs, TYR-317/TYR-320, and TYR-347/TYR-350 is mediated by epidermal growth factor receptor (EGFR), leading to inactivation of the protein's tumor suppressive function." (PMID 30417009, 2018). "EGFR expression was decreased in normal brain tissue and also in necrotic tumor tissue compared to viable tumor tissue." (PMID 29623552, 2018). "To comprehensively evaluate the increased risk of clinically relevant toxicities, we listed the incidences of anti‐EGFR‐relevant toxicity focusing on diarrhea and skin changes in the affected area of the skin involved in radiotherapy." (PMID 29464874, 2018). "The EGFR signaling pathway plays a crucial role in tumor processes since it modulates the cell cycle, inhibits apoptosis, induces angiogenesis, and promotes the motility of cancer cells and metastasis." (PMID 30670929, 2018). "EGFR overexpression is observed in many types of cancer, including head and neck, where it plays an important role in tumor proliferation, survival, vascularization, and metastasis." (PMID 30345256, 2018). "EGFR signalling is involved in a wide array of processes in tumor biology and tumorogenesis, including invasion and metastasis." (PMID 30288178, 2018). "The cooperative interaction of Src with EGFR is characterised by increased DNA synthesis and colony formation in soft agar in vitro and increased tumour incidence in vivo when c-Src- and EGFR-expressing cells are transplanted into nude mice." (PMID 29861494, 2018). "Gefitinib competes with adenosine triphosphate at the ATP binding site in epithelial cells, blocking its tyrosine kinase activity, and consequently inhibiting EGFR signaling pathway, which can induce tumor cell apoptosis." (PMID 29686393, 2018). "In contrast, the combination of EBRT with EGFR targeting endoradiotherapy was found to activate syngergistic principles for tumor eradication." (PMID 30042828, 2018). "In these patients, the growth and survival of tumor cells have become exclusively dependent on the aberrant activation of EGFR, termed an ‘oncogene-addicted’ state, and therefore, activated EGFR is an ideal therapeutic target." (PMID 29416720, 2018). "In order to address the impact of EGFR and EpCAM expression on tumor cell behavior at the mechanistic level, we established an in vitro mimic of the clinical situation." (PMID 30261040, 2018). "Wildtype for KRAS and a strong EGFR expression were detected in >90% of the tumor cells, thus addition of the EGFR monoclonal antibody cetuximab or panitumumab to a platinum-based chemotherapy was recommended." (PMID 30410678, 2018). "EGFR genotyping based on tumor tissue showed 19 deletions in 22 (44%) patients, L858R in 15 (30%), and wild-type EGFR in 13 (26%)." (PMID 30526536, 2018).
tumor (continued). "Other signalling pathways, including EGFR, Ras, Hippo and Myc have been previously examined, but were reported to be unchanged or only having some ectopic activation in ph tumours." (PMID 29357360, 2018). "In fact, EGFR inhibition combined with ER signaling disruption resulted in a marked inhibition of tumor xenograft growth." (PMID 30373552, 2018). "Mutations are mainly found in tumor suppressors (COSMIC), but common oncogenes such as PI3K, EGFR, and VEGFR are, if any, rarely found to be mutated in MPM, which limits the choice of targeted inhibitors." (PMID 29848954, 2018). "Tumor adaptation to treatment with EGFR antagonists thus involves metabolic reprogramming in HNSCC cells, enabling them to survive in vivo despite an impaired functional vasculature and hypoxic microenvironment." (PMID 30083516, 2018). "One hundred and three patients with first-line EGFR-TKIs treatment failure and rebiopsy tumor tissue available for testing were identified from TCVGH to evaluate the correlations in T790M detection." (PMID 30444875, 2018). "Otherwise, the uptake of radioactivity in the unblocked tumor appreciably exceeded uptake in any normal organ, providing a high-contrast image of EGFR-expressing xenograft." (PMID 30231504, 2018). "In contrast, virus with the EGFR-retargeting adapter resulted in luciferase expression in tumor cells, which were mainly observed as large patches." (PMID 29386504, 2018). "The MNT DTox-HMP-NLS-EGF with human EGF as a ligand module was designed as a platform for delivering a cytotoxic agent to the nucleus of tumor cells overexpressing EGFR." (PMID 30510514, 2018). "Another study demonstrated high levels of MET amplification seen in tumor biopsies of a mutant T790M EGFR NSCLC patient following osimertinib treatment." (PMID 29973561, 2018). "Based on this prevailing phenomenon, EGFR is therefore a rational and feasible target for suppression of tumor growth." (PMID 29570930, 2018). "The ARCHER 1009 (NCT01360554) and A7471028 (NCT00769067) studies randomly assigned advanced NSCLC patients to either dacomitinib or erlotinib, while EGFR alteration examination was performed centrally on archived tumor samples." (PMID 30680072, 2018). "Expression level of EGFR, pEGFR, and pAkt in cetuximab-treated TE-8 tumor markedly decreased compared to isotype-treated group." (PMID 30373221, 2018). "The PSMA aptamer-survivin siRNA-EGFR siRNA-PSMA aptamer chimera was able to inhibit EGFR and survivin simultaneously and induce apoptosis in vitro and in vivo suppressing both tumor growth and angiogenesis." (PMID 30384431, 2018). "The time course of H23 cell killing further revealed that tumor cells death occurred mainly after 4 h of EGFR-CAR T-cell co-culture and most cells were killed within 12 h of co-incubation." (PMID 29415996, 2018). "Although, the expression of EGFR in BxPC-3 and AsPC-1 tumor sections was similar, there was higher expression of HER3 in AsPC-1 when compared to BxPC-3." (PMID 29899472, 2018). "In particular, liquid biopsy is considered a valid alternative to tissue biopsy, representing a surrogate source of tumour DNA to monitor disease progression in first-line treatment of EGFR-mutant patients." (PMID 30430428, 2018). "In pulmonary adenocarcinoma patients with unexpected pleural spread detected during surgery, main tumor resection and EGFR-TKI therapy correlated with better survival." (PMID 29435191, 2018). "EGFR was pivotal in inducing tumor promotion and anti-apoptosis in cancer cells by inducing pAKT and NFκB." (PMID 30148841, 2018). "Dying tumor cells will be a source of NGcGM3 and EGFR together with some strong immune stimulatory signals." (PMID 29844873, 2018).
tumor (continued). "Hong and co-workers demonstrated that C225 binds EGFR in tumor tissue and forms EGFR/C225 complexes." (PMID 29470420, 2018). "A growing body of evidence through our experiments provides concrete data that inhibition of autophagy with 3-MA or HCQ followed by concomitant treatment with anti-EGFR mAbs and checkpoint inhibitors have a synergistic anti-tumor effect." (PMID 30427914, 2018). "The EGFR monoclonal antibodies BK011 and cetuximab inhibited tumor growth in a PDX model with EGFR amplification." (PMID 29433585, 2018). "Dimerized and phosphorylated EGFR then promotes its downstream signaling pathway, which promotes tumor cell proliferation, invasion, and metastasis by activating the expression of genes involved in cell adhesion, motility, growth, and angiogenesis." (PMID 30619732, 2018). "These proteins included EGFR (a receptor of the EGFR pathway that we found activated in QM-PDAC tumours), SOS1 and GRB2 (both of which are upstream signalling proteins in the canonical MAPK signalling pathway)." (PMID 30018740, 2018). "Based on this success different approaches for development of anti-EGFR based theragnostics was studied using different antibodies, chelators and radionuclide combinations for radioimmunotherapy of EGFR expressing tumor entities." (PMID 30042828, 2018). "EGFR is expressed on the cell surface of a wide variety of epithelium-derived solid tumors and most normal epithelial tissues, and the off-tumor toxicity related to CAR T-cell therapy is concerning." (PMID 29415996, 2018). "Recently, analysis of circulating tumor DNA revealed the emergence of distinct KRAS activating mutations (G12A, Q61H, and A146T) in three of 43 EGFR-mutant NSCLC patients with acquired activating mutations." (PMID 30445769, 2018). "One of the other targets of miR-140-3p is ITGB3 which cooperates with EGFR as a complex and is also a key factor in tumour cell adhesion and tumour angiogenesis." (PMID 30559931, 2018). "On the contrary, under these limiting conditions the bivalent α-EGFR-EGFR TM is still capable of activating UniCAR T cells for tumor cell killing." (PMID 29876011, 2018). "The results in the present study showed that SCC patients with objective responses had better PFS and OS benefits than those without responses, suggesting that patients with lung SCC have a better tumor response to EGFR‐TKIs would have a better prognosis." (PMID 30109777, 2018). "In this review, we summarized interactions of the EGFR and oxidative stress in tumor progression and TKI drug resistance." (PMID 29548337, 2018). "EGFR overexpression and its aberrant activity occur in over 90% of HNSCC cases and represent an independent prognostic marker correlating with increased tumor size, decreased radiation sensitivity, and increased risk of recurrence." (PMID 30389917, 2018). "89Zr-DFO-nimotuzumab was evaluated in vivo by microPET and ex vivo by biodistribution in healthy and EGFR-positive tumor bearing mice." (PMID 29682209, 2018). "Yet, it only achieved median progression-free survival of 4 months, and T cells exhaustion and non-specific toxicity were blamed for the less encouraging anti-tumor efficacy (as many tissues express EGFR at physiological conditions)." (PMID 29685162, 2018). "Actually, when ADC patients and non-ADC NSCLC patients were analyzed as a whole in our study, the primary tumor size of EGFR mutant patients was also smaller than that of EGFR wild-type patients (p = 0.02)." (PMID 29164298, 2018). "Moderate/strong EGFR protein expression was found in 59 (32.2%) of the tumours and 25 (13.7%) of the tumours had moderate/strong HER2 protein expression." (PMID 29046940, 2018).
tumor (continued). "By contrast, if cell death is prevented in the mutant cells by blocking caspase activity or upregulation of a cell survival pathway, such as the EGFR-Ras signalling pathway, then the cells survive and form invasive tumours." (PMID 29693007, 2018). "Combined treatment with NNK and arecoline synergistically facilitated tumor aggressiveness via EGFR–AKT signaling." (PMID 30148841, 2018). "We aimed to develop a reliable and easy preclinical mouse model to evaluate the efficacy of EGFR-targeted antibodies and examine the immune mechanisms involved in tumour regression." (PMID 29552307, 2018). "The activation of the epidermal growth factor receptor (EGFR) and downstream signaling of the Ras-Raf-MAP, PI3K, and Akt pathways are associated with the promotion of tumor growth, invasion, metastases, and the inhibition of apoptosis." (PMID 29391418, 2018). "Loss of PTEN has been shown to be involved in the development of resistance to EGFR-TKIs in certain tumor cell lines." (PMID 30445769, 2018). "In patients with metastatic colorectal cancer who received multiple chemotherapy treatments, especially, patients receiving anti‐EGFR treatment showed the strongest neoplasia T‐cell infiltration." (PMID 29658188, 2018). "This trial demonstrates that trastuzumab and paclitaxel treatment can induce objective tumour responses in patients with EGFR mutation positive NSCLC and HER2 expression after progression on EGFR TKI treatment." (PMID 30061586, 2018). "Even though the majority of HNSCC patient tumours express EGFR (∼98%), only approximately 15-20% of patients respond positively and benefit from this treatment." (PMID 29552307, 2018). "In total, these results indicate that activation of EGFR signaling during injury and inflammation improves tumor outcomes." (PMID 29904166, 2018). "The strongest prognostic factors were the pathologic nodal stage (pN + : HR 1.89) and pathologic tumor size (pT ≥ 20 mm: HR 1.47), followed by the histological grade, ERα positivity, the Ki-67 index, and EGFR expression (HR 1.32–1.39)." (PMID 29086231, 2018). "Higher expression of EGFR in oral squamous cell carcinomas have also been correlated with larger tumours and late stage, and hence, a poor prognosis." (PMID 30138436, 2018). "Anti-EGFR antibodies are added to the first-line treatment of metastatic colon cancer and this approach elicits more potent anti-tumor effect than conventional chemotherapies." (PMID 30158525, 2018). "Among 51 eligible cases, 35 cases undergone systemic anti-tumor therapy included systemic chemotherapy and/or EGFR-TKIs, and 16 cases didn’t have therapy or only have intrapleural injection of cisplatin." (PMID 30046124, 2018). "Oxidation of both the EGFR and downstream phosphatases by ROS enhances EGFR-mediated signaling and promotes tumor progression." (PMID 29548337, 2018). "Our results are in agreement with a previous study in which higher expression of IL-2, TNF-α, and granzyme B in CAR T cells was also observed, when similarly made CAR T cells were co-cultured with target tumor cells with EGFR or EGFRvIII." (PMID 29685162, 2018). "This review primarily focuses on the recent literature with respect to the roles of the EGFR and ROS and correlations between ROS and the EGFR in tumor progression and EGFR TKI resistance." (PMID 29548337, 2018). "Several reports in the literature have documented a functional relationship between the ganglioside GM3 and EGFR in the tumor cell membrane." (PMID 29844873, 2018). "Levels of MSI1/EGFR mRNA expression in tumor tissues from 48 ESCC patients were compared to their corresponding normal tissues using real-time polymerase chain reaction." (PMID 30202417, 2018). "Diverse strategies based on anti-EGFR antibodies, like Cetuximab and Nimotuzumab induce tumor shrinkage or stabilization, mainly in combination with chemotherapy or radiotherapy, but resistant tumor variants rapidly emerge." (PMID 29844873, 2018).
tumor (continued). "Overexpression of EGFR is commonly found in the tumour samples collected from HNSCC patients and it has been associated with poor prognosis and worse overall survival." (PMID 30001714, 2018). "In this study, the targeting effectiveness of gold nanoparticles conjugated with both antibody types (as well as non-targeted controls) was tested in vitro as well as in vivo in an EGFR-overexpressing mouse tumor model." (PMID 30408128, 2018). "Taken together, our results indicate that anti‐EGFR therapies will be successful in patients with FOS‐positive OS, where EGFR seems to be a tumor driver." (PMID 30361264, 2018). "Higher CD8+ tumor infiltrating lymphocytes (TILs) were spotted in the tumor microenvironment in response to EGFR mAb neoadjuvant therapy." (PMID 29455658, 2018). "When comparing the results for samples from the same run, we found that the number of reads for each EGFR exon was much higher in the patient’s tumour (by around 10-fold for exons 12 and 21, and 15-fold for exons 18, 19 and 20)." (PMID 30305059, 2018). "Altogether, these findings demonstrate that miR-133a-3p-mediated regulation of EGFR and HuR contributes to enhanced tumor growth, and possibly promotes metastasis." (PMID 30289952, 2018). "We also showed that these T cells were the effector and memory phenotype T cells because of high levels of T helper type 1 (Th1) cytokines generated with EGFR-positive tumor cells, thus indicating the cytotoxic effect of these EGFR-CAR T cells." (PMID 29415996, 2018). "The larger number of EGFR positive cells explains the findings on the level of RNA expression in tumor lysates especially if the stroma content is low in higher grade tumors with worse prognosis." (PMID 29989001, 2018). "BMI1, as well as other tumor promoting genes (like EGFR and LEF1) were significantly upregulated in NCH644 in contrast to our expectations (adjusted p-values calculated by DESeq2, · = p < 0.1, * = p < 0.05, ** = p < 0.01, *** = p < 0.0001)." (PMID 29724193, 2018). "Treatment with erlotinib (tyrosine kinase inhibitor [TKI] of epidermal growth factor receptor) plus gemcitabine in 10 patients resulted in tumor-size reduction in 1 patient, whereas 8 patients had progressive disease at first evaluation." (PMID 30348224, 2018). "Consistent with the in vitro results, overexpression of miR-133b significantly restrained the tumor growth and lung metastases via regulating EGFR/ITGB4/FAK/Grb2 signaling pathway." (PMID 30479571, 2018). "For instance, exosomes secreted by glioma cells transport and transfer EGFRvIII, a constitutively active oncogenic form of EGFR, then acceptor tumor cells show an increase in cell proliferation and survival." (PMID 30149660, 2018). "To understand the link between drug persisters and EMT, we have performed IHC analysis of EMT markers in vivo using xenograft tumor samples that were treated with control or EGFR TKI and demonstrated that EGFR TKI leads to upregulation of the EMT phenotype." (PMID 30097569, 2018). "For example, all imaging probes based on EGF have much higher uptake in liver than in tumors or the tumor-to-liver ratio is close to one, which precludes the use of such tracers for imaging of EGFR expression in hepatic metastases." (PMID 30231504, 2018). "As overexpression of EGFR in clinical tumor samples has previously been described, we then investigated EGFR in HNSCC using immunohistochemistry in order to assess the spatial distribution." (PMID 29989001, 2018). "These heavily pre-treated patients received the combination of lumretuzumab, a monoclonal anti-ErbB3 antibody, plus erlotinib, an anti-EGFR small molecule, showing tumor shrinkage." (PMID 29515761, 2018). "In this report, we explored the approach of using a low affinity EGFR ADC to preferentially target tumor cells that express medium to high level of EGFR." (PMID 30323890, 2018).